GSTM2 (glutathione S-transferase mu 2)
Description:
Conjugation of reduced glutathione to a wide number of exogenous and endogenous hydrophobic electrophiles. Participates in the formation of novel hepoxilin regioisomers.
Synonyms: GST4; GSTM; GSTM2-2; GTHMUS
Tractability: Small molecule: a structure with a bound ligand is known; a high-quality ligand is known; it has a high-quality binding pocket. PROTAC: ubiquitination databases record sites on it; its protein half-life has been measured; a small molecule that binds it is known.
Target class: Enzyme; Transferase
Chemical probes: NBDHEX, PD080881, PD081059, PD081319, PD081747, PD082143, PD082274, PD082630, PD082787, PD082815, PD082839, PD082861, PD083044, PD084091, PD084856
Gene: Protein-coding gene on chromosome 1 (109,667,348 to 109,709,551, forward strand). Ensembl gene ENSG00000213366.
Subcellular location: Cytoplasm
Subcellular location (Human Protein Atlas): Cytosol; Cytokinetic bridge; Microtubules; Primary cilium tip; Primary cilium transition zone; Vesicles
Pathways (Reactome):
Metabolism: Glutathione conjugation
Gene Ontology:
Molecular function: calcium channel inhibitor activity; enzyme binding; fatty acid binding; glutathione binding; glutathione peroxidase activity; glutathione transferase activity; protein binding; protein homodimerization activity; transmembrane transporter binding
Biological process: cellular detoxification of nitrogen compound; cellular response to caffeine; glutathione metabolic process; hepoxilin biosynthetic process; linoleic acid metabolic process; nitrobenzene metabolic process; regulation of cardiac muscle contraction by regulation of the release of sequestered calcium ion; regulation of release of sequestered calcium ion into cytosol by sarcoplasmic reticulum; regulation of skeletal muscle contraction by regulation of release of sequestered calcium ion; xenobiotic catabolic process; relaxation of cardiac muscle; cellular oxidant detoxification
Cellular component: cytoplasm; cytosol; extracellular exosome; sarcoplasmic reticulum
Genetic constraint (gnomAD): Loss-of-function variants: 26 observed, 25.44 expected, observed/expected ratio (o/e) 1.02, 90% interval 0.75 to 1.42. The upper end of that interval is the gene's LOEUF score, 1.42, which puts it in group 5 of 6, group 1 being the genes least tolerant of losing a copy. Missense variants: 180 observed, 222.6 expected, observed/expected ratio (o/e) 0.81, 90% interval 0.71 to 0.92. Synonymous variants: 76 observed, 78.13 expected, observed/expected ratio (o/e) 0.97, 90% interval 0.81 to 1.18.
Homologues: Orthologues: macaque GSTM5 (95% identical), rat Gstm2 (85% identical), mouse Gstm7 (83% identical), rabbit GSTM2 (76% identical), tropical clawed frog gstp1 (30% identical), zebrafish gstp1.1 (28% identical), Caenorhabditis elegans W10C8.4 (25% identical), Caenorhabditis elegans gst-1 (25% identical), Caenorhabditis elegans gst-23 (25% identical), Caenorhabditis elegans gst-35 (24% identical), Caenorhabditis elegans gst-14 (24% identical), Caenorhabditis elegans gst-16 (24% identical), and 33 more. Paralogues in human: GSTM1 (84% identical), GSTM4 (83% identical), GSTM5 (80% identical), GSTM3 (69% identical), GSTP1 (29% identical), GSTA1 (27% identical), GSTA2 (27% identical), GSTA3 (27% identical), GSTA5 (26% identical), GSTA4 (23% identical), HPGDS (23% identical).
Diseases named in the same sentence as GSTM2 in open-access papers:
GSTM2 is named in the same sentence as 70 diseases in open-access papers, as found by Europe PMC text mining. Sharing a sentence is not in itself a finding about the gene and the disease. The quoted sentences say what the papers report.
breast carcinoma (11 papers, 2014 to 2025). "Among these, 11 CNVRs overlapped with 12 genes (GSTM2, RAB40B, HLA_DRB5, HLA_DRB6, EYA1, DOCK3, ANKS1B, CACNA1C, RAB11FIP3, BAGE, SGCZ, POM121c) and were specifically associated with breast cancer risk and OS." (PMID 29116104, 2017). "Concerning the candidate genes identified as potential molecular biomarkers for rectal cancer, GFRA1, and GSTM2, aberrant methylation of GSTM2 has previously been identified in prostate cancer, breast cancer and oral squamous cell carcinoma." (PMID 27566576, 2016). "We also examined two gene regions (ESR1 and GSTM2) found to display hypermethylation preferentially in more aggressive breast cancers." (PMID 26510686, 2015). "Furthermore, KM plotter survival analysis for GSTM2 in breast cancer patients demonstrated a significantly poor overall survival associated with lower expression levels." (PMID 40426890, 2025). "Additionally, with adequate funding support gene knockdown experiments will be designed to investigate the influence of target genes, such as GSTM2 and ATP7B, on the biological behavior of breast cancer cells, thereby improving the functional depth and clinical relevance of the study." (PMID 41278297, 2025).
prostate carcinoma (11 papers, 2016 to 2025). A carcinoma that arises from epithelial cells of the prostate gland. "CYP2E1 is involved in xenobiotic detoxification but is also a driver of ROS production; FGFR1 is linked to proliferation and treatment resistance; and GSTM2 has been identified in antioxidant defense and has been associated with resilience to treatment and OS-induced stress in prostate cancer." (PMID 41009689, 2025). "In our study, we identified AOX1, APOC1, ARMCX1, FLRT3, GSTM2, and HPN as biomarkers associated with prostate cancer (PCa)." (PMID 37583929, 2023). "The possible prostate cancer (PCa) diagnostic biomarkers AOX1, APOC1, ARMCX1, FLRT3, GSTM2, and HPN were identified and validated using the GSE69223 and GSE71016 datasets." (PMID 37583929, 2023). "As the accumulation of deleterious mutations should adversely impact the fitness of a tumour, we were intrigued why an increased mutation rate is apparently selected for in prostate cancer via hypermethylation of GSTP1 and GSTM2." (PMID 34871444, 2021). "BIRC3 and PIM2 are recognized anti-apoptotic factors, and GSTM2 is a biomarker for the early stages of the prostate cancer." (PMID 34209090, 2021). "Similarly, we also found strong correlations of GSTM2 and GSTP1 promoter methylation with copy number alteration (CNA) burden in prostate cancer (Spearman’s ρ of 0.53 for GSTM2 and 0.49 for GSTP1), with both promoters among the promoters whose methylation is most strongly associated with CNA burden." (PMID 34871444, 2021). "Additionally, we have uncovered that putative epigenetic driver events, such as GSTP1 and GSTM2 hypermethylation in prostate cancer, may influence the acquisition of genetic driver events via their influence on the tumour mutation load." (PMID 34871444, 2021). "Together these observations suggest a general role for GSTM2 and GSTP1 in controlling genomic integrity, which is counter selected in prostate cancer." (PMID 34871444, 2021). "Both GSTM2 and GSTP1 promoters were among the top 1% of promoters whose methylation is most strongly correlated with TMB in prostate cancer demonstrating that this association is specific for these genes." (PMID 34871444, 2021). "Indeed, CNA burden has been previously shown to be a strong predictor of recurrence and survival in prostate cancer implicating methylation of GSTM2 and GSTP1 in the prognosis of prostate cancer patients via allowing for higher amount of genomic aberrations." (PMID 34871444, 2021). "Noni Extract could regulate GSTM2 expression to impeded angiogenesis and proliferation in prostate cancer patients." (PMID 35965498, 2022).
lung carcinoma (10 papers, 2007 to 2023). "This is line with several studies underlying GSTM2 has a chemoresistance marker including in lung cancer." (PMID 38006431, 2023). "GSTM2 efficiently alleviated benzo[a]pyrene-diolepoxide- or benzo[a]pyrene-diolepoxide-induced DNA damage in lung cancer cells." (PMID 38037116, 2023). "The high expression of GSTM2 is also correlated with the favorable survival of patients with lung cancer." (PMID 38111060, 2023). "The role of GSTM2 has been studied in lung cancer, where it was found to decrease benzo[a]pyrene-induced DNA damage in lung cancer cells." (PMID 33802702, 2021). "DNA methylation of the GSTM2 gene promoter decreases its gene expression by inhibiting Sp1 binding, and GSTM2 expression suppresses the migration of lung cancer cells." (PMID 33802702, 2021). "Glutathione S-transferase mu2 (GSTM2) is a phase II detoxification enzyme, which is often downregulated in lung cancer due to hypermethylation of its promoter." (PMID 33282950, 2020). "We also found hypermethylation of GSTM2, a gene that is normally high expressed in ovary, but has been shown to be a hypermethylated in lung cancers and colorectal cancers, suggesting a tumor suppressor role for GSTM2 across tissues." (PMID 31356589, 2019). "GSTM2 plays an important role in the development and metastasis of lung cancer." (PMID 38111060, 2023). "In addition to GSTM5, human GSTM2 has been found to be silenced by promoter hypermethylation in lung cancer cells, and GSTM2, 3 and 5 promoter hypermethylation was also found in Barrett’s adenocarcinoma." (PMID 27404495, 2016). "GSTM2 has shown the ability to increase the expression of CCN2 and inhibit lung cancer migration." (PMID 33282950, 2020).
hepatoma (6 papers, 2014 to 2023). "By using a cutoff value of β > 0.5, we identified five DME genes (CYP1B1, CYP8B1, GSTM2, GSTP1, and UGT3A2) that were regulated by DNA methylation in hepatoma cells." (PMID 26421064, 2015). "Among these DME genes, the downregulation of CYP1B1, CYP8B1, GSTM2, GSTP1, UGT2B15, and UGT3A2 in hepatoma cells could be explained by DNA methylation status." (PMID 26421064, 2015).
Obesity (5 papers, 2006 to 2025). Accumulation of substantial excess body fat.
colon cancer (4 papers, 2016 to 2025). "To further clarify the mechanism of GSTM2 in tumorigenesis, we analyzed genome-wide mutation differences in GSTM2-high-expression and low-expression colon cancer patients." (PMID 36263204, 2022). "Our results revealed that the GSTM2 expression was probably positively associated with the infiltration ratios of most immune cells in colon cancer, such as CD8+ T cells." (PMID 36263204, 2022). "To understand the underlying mechanism by which GSTM2 affected the development of colon cancer, we first collected a total of 5538 co-expressing mRNAs of GSTM2 from the linkedomics database." (PMID 36263204, 2022). "To explore the possible reasons for the down-regulation of GSTM2 in colon cancer, we first studied the DNA mutations of GSTM2." (PMID 36263204, 2022). "By analyzing the data sets from the cBioportal database (n = 4488), we found GSTM2 had a moderate mutation frequency in colon cancer patients (1%-4%), and about 50% of these mutations were deep deletion." (PMID 36263204, 2022). "Third, we identified two potential causes of down-regulation of GSTM2 expression in colon cancer." (PMID 36263204, 2022). "As a result, GSTM2 expression was negatively associated with MSI in colon cancer." (PMID 36263204, 2022). "Therefore, we speculated that the functions of GSTM2 in colon cancer carcinogenesis might be related to PCDH17 mutation." (PMID 36263204, 2022). "Therefore, the GSTM2 mRNA expression was potentially associated with the survival of colon cancer patients, and GSTM2 might be served as a prognostic marker for colon cancer." (PMID 36263204, 2022). "After that, we used TIMER database to analyze the relationship between GSTM2 expression and the infiltration levels of six kinds of classical immune cells in TCGA colon cancer patients." (PMID 36263204, 2022). "In our previous proteomic study (ntumor = 8, nnormal = 8), we observed an extreme decrease in the expression of GSTM2 in colon tumor tissues versus normal adjacent tissues." (PMID 36263204, 2022). "We confirmed the GSTM2 expression in Chinese patients and its effect on the occurrence of colon cancer." (PMID 36263204, 2022). "To confirm the GSTM2 expression in colon cancer, we first analyzed the GSTM2 protein expression in human colon cancer tissues and normal adjacent tissues using our own proteomic data (n = 8, samples of the same stage were pooled into one sample)." (PMID 36263204, 2022). "There was a significant correlation between the GSTM2 mRNA expression and stromal score, microenvironment score, and immunity score in colon cancer (p < 0.001)." (PMID 36263204, 2022). "The lower expression of GSTM2 in stem cells further illustrates this gene’s potential importance and functions in tumorigenesis of colon cancer." (PMID 36263204, 2022). "Eventually, we identified RAD21 and SP1 as potential transcription factors of GSTM2 in colon cancer." (PMID 36263204, 2022). "Because transcription factors are frequently connected with the expression of target genes, we used transcriptome data of colon cancer tissues to determine which transcription factors were more likely to co-express with GSTM2." (PMID 36263204, 2022). "In this study, using the RNA-Seq datasets of colon cancer patients from public database (ntumor = 457, nnormal = 41), we confirmed the reduced expression of GSTM2 and its prognostic value in colon cancer." (PMID 36263204, 2022). "To confirm the correlation between the GSTM2 expression and immune microenvironment, we used six distinct algorithms to assess the correlation between the GSTM2 expression and immune cell infiltration in human colon cancer." (PMID 36263204, 2022). "Based on the results of three data sets named GSE17536, GSE17537, GSE12945, we demonstrated that colon cancer patients with lower expression of GSTM2 had worse overall survival rates (OS), disease-free survival (DFS) and disease specific survival rates (DSS)." (PMID 36263204, 2022).
colon cancer (continued). "Subsequently, we uncovered two potential reasons for the lower expression of GSTM2 in colon cancer tissues, including the deep deletion of GSTM2 on genome, and the up-regulation of RAD21 or SP1." (PMID 36263204, 2022). "Univariate and multivariate analyses identified GSTM2 level in lymphocytes as an independent prognostic factor for colon cancer." (PMID 36263204, 2022). "In this study, we studied the mRNA and protein expression of GSTM2 in colon cancer tissues and normal colon tissues using the public data sets." (PMID 36263204, 2022). "Further, we revealed the possible pathways by which GSTM2 affected the colon cancer tumorigenesis, and investigated the correlation between the GSTM2 expression and the infiltration ratios of immune cells." (PMID 36263204, 2022). "A previous study has proclaimed that the butyrate can induce the GSTM2 expression in colon cancer, implying that GSTM2 may increase the detoxification ability of colon mucosa and play a protective role." (PMID 36263204, 2022). "Also, the survival analysis revealed colon cancer patients with low GSTM2 protein expression had a shorter overall survival." (PMID 36263204, 2022). "To clarify the functional role and prognostic value of GSTM2 in colon cancer, we further analyzed the relationship between the GSTM2 expression and prognosis of colon cancer patients using four data sets from Gene Expression Omnibus (GEO) collected by the Prognoscan database." (PMID 36263204, 2022). "First, we discovered three GSTM2 transcription factors in colon tissues using the TFtarget database, and we suspected that in colon cancer tissues, these transcription factors might probably launch GSTM2’s transcription." (PMID 36263204, 2022). "We predicted the potential upstream transcription factors of GSTM2 in colon cancer tissues." (PMID 36263204, 2022). "Whereas, the functions of GSTM2 in colon cancer are barely known." (PMID 36263204, 2022). "In conclusion, we uncovered the prognostic value of GSTM2 based on the public data and our own data, revealed its potential regulatory role in tumor immune microenvironment, and disclosed the probable reasons for its lower expression in colon cancer." (PMID 36263204, 2022). "Additionally, we investigated the expression changes of the potential transcription factors of GSTM2 in colon cancer tissues versus normal tissues." (PMID 36263204, 2022). "All in all, our results are consistent with the previous studies, and the function of RAD21 in colon cancer further indicates that GSTM2 may be involved in tumor formation as a suppressor." (PMID 36263204, 2022). "Our findings here suggest that GSTM2 may serve as a prognostic biomarker for colon cancer, and as a potential drug target for immunotherapy." (PMID 36263204, 2022). "Furthermore, we used our own Chinese cohort (ntumor = 100, nnormal = 72) verified the lower GSTM2 expression in colon cancer, and also its effects on patient prognosis." (PMID 36263204, 2022). "In colon cancer, MSI was highly associated with immune cell infiltration and patients’ clinical response to immunotherapy, thus we evaluated the correlation between GSTM2 expression and MSI in various cancers." (PMID 36263204, 2022). "Therefore, of the three genes, the expression of RAD21 and SP1 in colon cancer matched the results of correlation analysis, so that RAD21 and SP1 might be the potential upstream transcription factors of GSTM2 in colon cancer." (PMID 36263204, 2022). "Consequently, the up-regulation of RAD21 and SP1 might be the second probable reason for the down-regulated expression of GSTM2 in colon cancer." (PMID 36263204, 2022). "Moreover, we disclosed that GSTM2 might be involved in several immune-related pathways in colon cancer, such as chemokine signaling and leukocyte transendothelial migration." (PMID 36263204, 2022). "Furthermore, we uncovered the potential immunological functions of GSTM2 in colon cancer." (PMID 36263204, 2022).